Y_RNA (Y RNA )
Gene: Miscellaneous RNA gene on chromosome 8 (14,332,555 to 14,332,663, forward strand). Ensembl gene ENSG00000206950.
Homologues: Orthologues: chimpanzee Y_RNA (97% identical), macaque Y_RNA (91% identical). Paralogues in human: Y_RNA (87% identical), Y_RNA (85% identical), RNY1P5 (84% identical), Y_RNA (83% identical), RNY1P6 (82% identical), Y_RNA (82% identical), RNY1 (81% identical), Y_RNA (81% identical), Y_RNA (80% identical), Y_RNA (79% identical), RNY1P1 (78% identical), RNY1P11 (78% identical), and 94 more.